NUP43 (nucleoporin 43)
Description:
Component of the Nup107-160 subcomplex of the nuclear pore complex (NPC). The Nup107-160 subcomplex is required for the assembly of a functional NPC. The Nup107-160 subcomplex is also required for normal kinetochore microtubule attachment, mitotic progression and chromosome segregation.
Synonyms: bA350J20.1; FLJ13287; p42
Tractability: PROTAC: ubiquitination databases record sites on it; its protein half-life has been measured.
Gene: Protein-coding gene on chromosome 6 (149,724,315 to 149,750,286, reverse strand). Ensembl gene ENSG00000120253.
Subcellular location: Chromosome, centromere, kinetochore; Nucleus, nuclear pore complex
Subcellular location (Human Protein Atlas): Nuclear speckles; Nucleoplasm; Cytosol
Pathways (Reactome):
Disease: Defective TPR may confer susceptibility towards thyroid papillary carcinoma (TPC); HCMV Early Events; HCMV Late Events; NEP/NS2 Interacts with the Cellular Export Machinery; NS1 Mediated Effects on Host Pathways; Nuclear import of Rev protein; Rev-mediated nuclear export of HIV RNA; SARS-CoV-2 activates/modulates innate and adaptive immune responses; Transport of Ribonucleoproteins into the Host Nucleus; Viral Messenger RNA Synthesis; Vpr-mediated nuclear import of PICs
Cell Cycle: Amplification of signal from unattached kinetochores via a MAD2 inhibitory signal; EML4 and NUDC in mitotic spindle formation; Mitotic Prometaphase; Nuclear Pore Complex (NPC) Disassembly; Postmitotic nuclear pore complex (NPC) reformation; Resolution of Sister Chromatid Cohesion; Separation of Sister Chromatids
Metabolism of RNA: Transport of Mature mRNA Derived from an Intronless Transcript; Transport of Mature mRNA derived from an Intron-Containing Transcript; Transport of the SLBP Dependant Mature mRNA; Transport of the SLBP independent Mature mRNA; snRNP Assembly; tRNA processing in the nucleus
Metabolism of proteins: SUMOylation of DNA damage response and repair proteins; SUMOylation of DNA replication proteins; SUMOylation of RNA binding proteins; SUMOylation of SUMOylation proteins; SUMOylation of chromatin organization proteins; SUMOylation of ubiquitinylation proteins
Metabolism: IP3 and IP4 transport between cytosol and nucleus; IP6 and IP7 transport between cytosol and nucleus; IPs transport between nucleus and cytosol; Regulation of Glucokinase by Glucokinase Regulatory Protein
Cellular responses to stimuli: Regulation of HSF1-mediated heat shock response
Immune System: ISG15 antiviral mechanism
Signal Transduction: RHO GTPases Activate Formins
Gene Ontology:
Molecular function: protein binding
Biological process: nucleocytoplasmic transport
Cellular component: kinetochore; nuclear envelope; nuclear pore outer ring; nucleoplasm; cytosol; nuclear pore
Genetic constraint (gnomAD): Loss-of-function variants: 21 observed, 35.87 expected, observed/expected ratio (o/e) 0.59, 90% interval 0.41 to 0.84. The upper end of that interval is the gene's LOEUF score, 0.84, which puts it in group 3 of 6, group 1 being the genes least tolerant of losing a copy. Missense variants: 354 observed, 376.13 expected, observed/expected ratio (o/e) 0.94, 90% interval 0.86 to 1.03. Synonymous variants: 113 observed, 132.28 expected, observed/expected ratio (o/e) 0.85, 90% interval 0.73 to 1.
Homologues: Orthologues: chimpanzee NUP43 (99% identical), macaque NUP43 (99% identical), dog NUP43 (95% identical), pig NUP43 (95% identical), mouse Nup43 (94% identical), rabbit NUP43 (94% identical), guinea pig Nup43 (91% identical), rat Nup43 (86% identical), tropical clawed frog nup43 (69% identical), zebrafish nup43 (61% identical), Drosophila melanogaster Nup43 (26% identical), Caenorhabditis elegans npp-23 (21% identical).
Diseases named in the same sentence as NUP43 in open-access papers:
NUP43 is named in the same sentence as 10 diseases in open-access papers, as found by Europe PMC text mining. Sharing a sentence is not in itself a finding about the gene and the disease. The quoted sentences say what the papers report.
breast carcinoma (8 papers, 2019 to 2025). "Other members of the nucleoporin family have been linked with cancer including Tpr, NUP62, NUP214 and NUP358/RanBP2 with NUP88 and more recently, NUP43 specifically linked to poor outcome in breast cancer." (PMID 30935371, 2019). "NUP43 overexpression contributes to the advancement of multiple malignant cancers, including gastric cancer, breast cancer, and ovarian cancer." (PMID 38762481, 2024). "RBBP4 is involved in apoptosis in early mouse embryonic development, and NUP43 plays a crucial role in various cancers, including breast cancer and gastric cancer." (PMID 37547318, 2023). "In particular, high expression of Nucleoporin 43 (NUP43), one of the top downregulated genes in our study, is associated with DNA amplification and poor overall survival in luminal A and HER2+ breast cancer tumors." (PMID 35887085, 2022). "The upregulation of NUP43 is associated with DNA amplification, which can independently predict the overall survival rate of lumen A and HER2+ breast cancer." (PMID 33584825, 2021). "Previous research has indicated that PGK1, SDC1, SDC3, NUP43, and IL13RA1 may contribute to the development and progression of breast cancer." (PMID 39590319, 2024).
ovarian carcinoma (2 papers, 2021 to 2024). A malignant neoplasm originating from the surface ovarian epithelium. "Our further qRT-PCR showed that seven hub genes (BUB1, KIF2C, NUP43, NDC80, NUF2, CCNB2 and CENPN) were differentially expressed in platinum-resistant ovarian cancer cells." (PMID 34820170, 2021).
breast tumors (1 paper, 2022). "Studies have shown that the upregulation of NUP43 is associated with poorer OS in luminal A and HER2+ breast tumors." (PMID 35535040, 2022).
chronic myeloid leukemia (1 paper, 2021). "MiRNA-409-5p inhibits proliferative potential and cell cycle progression in child chronic myeloid leukemia (CML) by upregulation of NUP43 expression." (PMID 33584825, 2021).
glioma (1 paper, 2023). A benign or malignant brain and spinal cord tumor that arises from glial cells (astrocytes, oligodendrocytes, ependymal cells). "In the group of genes with decreased expression, there was a correlation with WDR82 in pediatric glioma tissue specimens, and representative results are shown for NUP43 and PKYMT1." (PMID 37444539, 2023).
cancer (6 papers, 2019 to 2025). A tumor composed of atypical neoplastic, often pleomorphic cells that invade other tissues. "In GC, NUP43 is closely linked to prognosis, especially in the high-risk group, where its expression correlated with immune scores, immune cell infiltration, and the enrichment of cancer and immune pathways." (PMID 40821814, 2025). "The results revealed a significantly higher expression of NUP43 in cancer tissues compared to neighboring tissues." (PMID 38762481, 2024). "NUP43 has not yet been shown to be associated with any forms of human cancer in contrast to other members of the NUP gene family." (PMID 31709175, 2019).
tumor (5 papers, 2021 to 2024). "Significantly, our findings indicate that the increased expression of NUP43 in patients with CRC plays a role in the buildup of PD-L1 within the nucleus of tumor cells." (PMID 38762481, 2024). "In this study, we employed the C57/B6 mouse subcutaneous tumor-bearing model to assess the impact of NUP43 in vivo." (PMID 38762481, 2024). "We aslo analyzed the differential expression of PGK1, SDHC, PFKL, and NUP43 in tumor and normal samples." (PMID 33584825, 2021). "The results showed that CACNA1H, IL13RA1, NUP43, PGK1, and SDC1 were highly expressed in tumor samples, while expression of AK3 was significantly decreased." (PMID 34600547, 2021).
NUP43 also shares sentences with these, for which no sentence is quoted: gastric cancer (2 papers); colorectal cancer (1); lung carcinoma (1).